PTOV1 (PTOV1 extended AT-hook containing adaptor protein)
Description:
May activate transcription. Required for nuclear translocation of FLOT1. Promotes cell proliferation.
Synonyms: PTOV-1; ACID2
Tractability: Antibody: UniProt places it where antibodies can reach, with high confidence; its Gene Ontology location is reachable by antibodies, with medium confidence. PROTAC: UniProt records ubiquitination sites on it; ubiquitination databases record sites on it; its protein half-life has been measured.
Gene: Protein-coding gene on chromosome 19 (49,850,735 to 49,860,744, forward strand). Ensembl gene ENSG00000104960.
Subcellular location: Cytoplasm; Nucleus; Cell membrane; Cytoplasm, perinuclear region
Subcellular location (Human Protein Atlas): Nucleoplasm
Gene Ontology:
Biological process: positive regulation of transcription by RNA polymerase II
Cellular component: cytoplasm; nucleoplasm; nucleus; plasma membrane; transcription regulator complex; perinuclear region of cytoplasm
Genetic constraint (gnomAD): Loss-of-function variants: 20 observed, 55.65 expected, observed/expected ratio (o/e) 0.36, 90% interval 0.25 to 0.52. The synonymous counts are far from expectation, so gnomAD's model fits this gene poorly and the ratio says little. Missense variants: 589 observed, 539.44 expected, observed/expected ratio (o/e) 1.09, 90% interval 1.02 to 1.17. Synonymous variants: 333 observed, 226.13 expected, observed/expected ratio (o/e) 1.47, 90% interval 1.35 to 1.61.
Homologues: Orthologues: chimpanzee PTOV1 (99% identical), macaque PTOV1 (99% identical), dog PTOV1 (97% identical), mouse Ptov1 (97% identical), rat Ptov1 (97% identical), pig PTOV1 (96% identical), guinea pig PTOV1 (69% identical), zebrafish med25 (34% identical), Drosophila melanogaster CG13609 (21% identical), Drosophila melanogaster MED25 (19% identical). Paralogues in human: MED25 (40% identical).
Diseases named in the same sentence as PTOV1 in open-access papers:
PTOV1 is named in the same sentence as 27 diseases in open-access papers, as found by Europe PMC text mining. Sharing a sentence is not in itself a finding about the gene and the disease. The quoted sentences say what the papers report.
prostate carcinoma (16 papers, 2014 to 2024). A carcinoma that arises from epithelial cells of the prostate gland. "Overexpression of PTOV1 causes the expression of c-Jun both total and in phosphorylated form in prostate cancer cells." (PMID 31083670, 2019). "In pre-neoplastic lesions of High Grade Prostate Epithelial Neoplasia, HGPIN, associated with prostate carcinomas, PTOV1 expression is increased compared to the normal prostate epithelium." (PMID 28029646, 2017). "Supporting previous findings of PTOV1 activity associated to more aggressive, potentially resistant stages, we show that docetaxel resistant prostate cancer cells express increased levels of PTOV1 concomitantly with genes associated to resistance." (PMID 28938627, 2017). "PTOV1 was associated with ribosomes and its overexpression promoted global protein synthesis in prostate cancer cells and COS-7 fibroblasts in a mTORC1-dependent manner." (PMID 26225961, 2015). "Prostate tumor overexpressed-1 (PTOV1), a modulator of the Mediator transcriptional regulatory complex, is expressed at high levels in prostate cancer and other neoplasias in association with more aggressive disease." (PMID 26225961, 2015). "PTOV1 was initially implicated in stimulation of prostate carcinoma cells’ proliferation, and its overexpression was reported to be a more general feature associated with neoplastic cells, especially in human high-grade malignant tumors." (PMID 26305455, 2015). "Aberrant PTOV1 expression is associated with tumor progression in prostate cancer and other neoplasms." (PMID 24947166, 2014). "This could have relevance to human biology since PTOV1 has been associated with prostate cancer, and the splicing event is likely to have a disruptive impact on one of the two major domains involved in the interaction with multiple other genes." (PMID 39075577, 2024). "PTOV1 action was previously found associated to cell cycle progression of prostate cancer cells." (PMID 28938627, 2017). "PTOV1 is an adaptor protein with functions in diverse processes, including gene transcription and protein translation, whose overexpression is associated with a higher proliferation index and tumor grade in prostate cancer (PC) and other neoplasms." (PMID 24684754, 2014). "However, the R117L/Q mutation found in LSCC and prostate cancer respectively, has a predicted functional impact score of medium, suggesting it might be a critical change for the function of PTOV1 in these tumors." (PMID 28029646, 2017). "To study whether the associations of PTOV1 with self-renewal and docetaxel resistant genes found here are detectable in metastasis, we interrogated database containing information from metastatic lesions of prostate cancer patients." (PMID 28938627, 2017). "The prostate tumor overexpressed-1 (PTOV1) is a protein with 80% overexpression in patients with prostate intraepithelial neoplasia, and it's linked to prostate cancer progression." (PMID 38622735, 2024). "Further analysis showed the interaction of ZYX with PTOV1 (commonly overexpressed in prostate cancer) and CBP proteins (RA receptor coactivator), resulting in attenuation of the cytotoxic effect of RA." (PMID 35740950, 2022). "After showing in human prostate cancer cells that PTOV1 expression correlates with Notch targets’ repression, the authors used Drosophila to study the interactions between PTOV1 and Notch." (PMID 34572036, 2021). "Prostate tumor overexpressed-1 (PTOV1) was firstly depicted as gene and protein overexpressed in prostate cancers and preneoplastic lesions of high-grad intraepithelial neoplasia." (PMID 34918668, 2021). "This is the case of a study from 2014, which focuses on PTOV1, an adaptor protein able to modulate proliferation and the cell cycle, which is overexpressed during prostate cancer." (PMID 34572036, 2021). "Prostate Tumor Overexpressed 1 (PTOV1) was initially identified during screening for genes overexpressed in prostate cancer." (PMID 31387622, 2019).
prostate carcinoma (continued). "A recent study reported that overexpressed PTOV1 plays a major role in tumorigenesis and progression of esophageal cancer and in prostate cancer." (PMID 31552087, 2019). "Later, it was found that high levels of PTOV1 correlated with poor prognosis of prostate cancer, breast cancer, urothelial carcinoma and so on." (PMID 31387622, 2019). "In prostate cancer cells, transduction of PTOV1 induced prostatospheres formation and self-renewal genes expression." (PMID 31387622, 2019). "Overexpression of PTOV1 has been found in multiple cancers such as prostate cancer, breast cancer, and liver cancer." (PMID 31387622, 2019). "Our findings identify PTOV1 as a promoter of docetaxel-resistance and self-renewal characteristics for castration resistant prostate cancer." (PMID 28938627, 2017). "The oncogenic protein PTOV1, first described in prostate cancer, was reported as overexpressed and significantly correlated with poor survival in numerous tumors." (PMID 28938627, 2017). "Prostate-Tumor-Overexpressed-1 (PTOV1) is a conserved adaptor protein discovered as overexpressed in prostate cancer." (PMID 28029646, 2017). "Increased mRNA and protein levels of PTOV1 were shown to correlate with prostate cancer progression and to promote CSCs-like properties." (PMID 28938627, 2017). "Gene amplifications for PTOV1 are frequent in prostate carcinomas, pancreas and present in other tumors." (PMID 28029646, 2017). "All together our findings indicate that PTOV1 confers prostate cancer cells the advantages to survive docetaxel toxicity, through upregulation of ABCB1 and genes associated to docetaxel resistance and pluripotency factors." (PMID 28938627, 2017). "In contrast to its low levels in benign prostate derived RWPE1 cells, PTOV1 is strongly expressed in most prostate carcinoma cell lines." (PMID 28938627, 2017). "Here, we investigated the role of PTOV1 in prostate cancer survival to docetaxel and self-renewal ability." (PMID 28938627, 2017). "Prostate tumor overexpressed-1 (PTOV1), first identified in prostate cancer, is a key factor in tumor progression and correlates with unfavorable clinical outcomes." (PMID 26992242, 2016). "PTOV1 was first identified in prostate cancer during a differentially screening for genes expression." (PMID 26992242, 2016). "In vivo, PTOV1 antagonizes Notch function in the Drosophila melanogaster wing, and it is required for full tumor growth and metastatic potentials of PC-3 prostate cancer cells in an immunodeficient mouse model." (PMID 24684754, 2014). "Our evidences link the pro-oncogenic and pro-metastatic effects of PTOV1 in prostate cancer to its inhibitory activity on Notch signaling and are supportive of a tumor suppressor role of Notch in prostate cancer progression." (PMID 24684754, 2014). "Recently, PTOV1 was shown to force cells to enter S phase and to promote mitotic activity of prostate cancer cells." (PMID 24947166, 2014). "The overexpression of PTOV1 in prostate cancer may be due to the cumulative effect of genes residing on chromosome 19." (PMID 31083670, 2019). "PTOV1 was firstly identified and reported to be overexpressed in prostate cancer." (PMID 31387622, 2019). "The role of PTOV1 in cell cycle progression has been studied in prostate cancer cells." (PMID 31083670, 2019). "Because docetaxel resistant prostate cancer cells show an increased expression of PTOV1, we have determined the effects of its knockdown using two different shRNAs directed to different sequences of the gene PTOV1, in both docetaxel sensitive and resistant cells." (PMID 28938627, 2017). "PTOV1 was previously demonstrated to be pro-oncogenic in prostate cancer." (PMID 28938627, 2017). "Similarly to prostate carcinomas, the subcellular distribution of PTOV1 in breast cancer and nasopharyngeal carcinomas was detected both in the nucleus and cytoplasm of carcinomatous cells." (PMID 28029646, 2017).
prostate carcinoma (continued). "Altogether, our findings indicate that the overexpression of PTOV1 in prostate cancer promotes the acquisition of resistance to chemotherapy with docetaxel that is parallel to the increase in self-renewal properties of prostate cancer cells." (PMID 28938627, 2017). "Ectopic expression of PTOV1 was first identified in prostate cancer." (PMID 26992242, 2016). "PTOV1 was first identified as a novel elevated expressed gene in prostate cancer." (PMID 24947166, 2014). "Recently, it was shown that PTOV1 promotes the in vitro formation of spheres in HaCaT transformed keratinocytes and PC3 prostate cancer cells, and promoted tumor growth in vivo." (PMID 28029646, 2017). "Prostate tumor overexpressed 1 (PTOV1), a 46 kDa protein with two repeated PTOV homology blocks, was first identified during a screen for genes overexpressed in prostate cancer." (PMID 24947166, 2014). "In the nucleus, PTOV1 acts as a transcriptional repressor of HES1 and HEY1 genes, two main targets of the Notch receptor, thus revealing its oncogenic function in counteracting the tumor suppressor action of Notch signaling in advanced prostate cancer." (PMID 28938627, 2017). "Thus, PTOV1 expression was analyzed in Du145 and PC3 prostate cancer cells rendered resistant to docetaxel in vitro as representative models of CRPC progression to a docetaxel resistant (DR) stage." (PMID 28938627, 2017).
breast carcinoma (7 papers, 2014 to 2025). "The results showed that PTOV1 is significantly upregulated in breast cancer, and overexpression of PTOV1 is closely associated with the clinical stage, T, N and M classification, and estrogen receptor (ER) expression levels in breast cancer." (PMID 24947166, 2014). "Taken together, these results suggested that upregulation of PTOV1 is associated with breast cancer progression." (PMID 24947166, 2014). "In the present study, we provided the first evidence that overexpression of PTOV1 protein is associated with poor prognosis of breast cancer patients with both early- and late-stage disease." (PMID 24947166, 2014). "The PTOV1 gene is located on a region of chromosome 19 (19q13) that is associated with high risk of breast cancer." (PMID 24947166, 2014). "Moreover, high expression of PTOV1 in breast cancer is strongly associated with clinicopathological characteristics and estrogen receptor expression status (P = 0.003)." (PMID 24947166, 2014). "Our study showed that PTOV1 is upregulated in breast cancer cell lines and clinical samples, and its expression was positively associated with progression and aggressiveness of breast cancer, suggesting that PTOV1 could serve as an independent prognostic marker." (PMID 24947166, 2014). "Taken together, our data showed that overexpression of PTOV1 is positively correlated with clinical stage; T, N, M classification; and ER expression levels, which further supported the hypothesis that the elevated PTOV1 expression is associated with breast cancer progression." (PMID 24947166, 2014). "Here, we have shown that PIN1 and PTOV1 knockdown arrests breast cancer cell MDA-MB-231 in the G2/M phase of the cell cycle before entry into the mitosis where rapid synthesis of proteins is required for cell division." (PMID 31083670, 2019). "Recently, PTOV1 was shown to increase the proportion of cells in the side population (SP) through the activation of Wnt/β-catenin signaling in breast cancer." (PMID 28938627, 2017). "The correlation of the overexpression of PTOV1 with tumor progression and poor survival is confirmed in breast cancer." (PMID 28938627, 2017). "In human breast carcinoma, high levels of PTOV1 expression correlated with high levels of nuclear β-catenin and low levels of DKK1." (PMID 28029646, 2017). "The overexpression of PTOV1 in breast cancer cell lines induced the nuclear translocation of β-catenin and increased β-catenin/TCF transcriptional activity." (PMID 28029646, 2017). "In breast cancer, 99.4% of the cancer samples analyzed expressed PTOV1, of which 49.1% showed high expression." (PMID 28029646, 2017). "This study aimed to investigate the expression and clinicopathological significance of PTOV1 in breast cancer." (PMID 24947166, 2014). "Statistical analysis was performed to evaluate the clinical significance between the PTOV1 expression and the clinicopathological parameters of breast cancer." (PMID 24947166, 2014). "Our data showed that PTOV1 is upregulated in breast cancer cell lines and in clinical tumor specimens, at both the mRNA and protein levels, compared with normal breast epithelial cells and normal breast tissues, respectively." (PMID 24947166, 2014). "In line with the finding of protein expression, the mRNA expression of PTOV1 was significantly higher in breast cancer cell lines than in NMEC." (PMID 24947166, 2014). "In the present study, e aimed to investigate the expression of PTOV1 in breast cancer and its relationship with clinical parameters and prognosis in breast cancer patients." (PMID 24947166, 2014). "Breast cancer patients with higher PTOV1 expression had substantially shorter survival times than patients with lower PTOV1 expression (P < 0.001)." (PMID 24947166, 2014). "Immunohistochemistry was performed to assess PTOV1 protein expression in 169 paraffin-embedded, archived breast cancer samples." (PMID 24947166, 2014).
breast carcinoma (continued). "The median survival time of patients with breast cancer with low PTOV1 expression was 115 months, compared with 78 months for patients with high PTOV1 expression." (PMID 24947166, 2014). "High PTOV1 expression was observed in areas containing primary breast cancer cells; however, it was undetectable or only marginally detectable in normal breast tissues and adjacent non-cancerous tissues." (PMID 24947166, 2014). "Our data revealed that PTOV1 was frequently overexpressed in breast cancer cell lines compared to normal human breast epithelial cells and in primary breast cancer samples compared to adjacent noncancerous breast tissues, at both the mRNA and protein levels." (PMID 24947166, 2014). "Higher PTOV1 protein expression was observed in all 12 breast cancer cell lines compared with that in two primary cultured normal human mammary epithelial cells (NMEC), in which it was weakly detected." (PMID 24947166, 2014). "Assessment of patient survival by the Kaplan–Meier analysis indicated an adverse correlation between PTOV1 expression and overall survival time of patients with breast cancer (P < 0.001)." (PMID 24947166, 2014). "In this study, we found that PTOV1 overexpression is correlated with breast cancer progression and progressive phenotype." (PMID 24947166, 2014). "The mRNA and protein expression levels of PTOV1 were analyzed in 12 breast cancer cell lines and eight paired breast cancer tumors by semi-quantitative real time-PCR and western blotting, respectively." (PMID 24947166, 2014). "Very recently, PTOV1 expression was shown to activate Wnt/β-catenin signaling in breast cancer." (PMID 28029646, 2017). "The significant association between PTOV1 and ABCB1 transporter expression, a protein also implicated in the modulation of the stemness phenotype in cancer cells, is in agreement with previous data showing PTOV1 promoting self-renewing properties of prostate and breast cancer cells." (PMID 28938627, 2017). "To further explore whether PTOV1 upregulation is associated with clinicopathological characteristics of breast cancer, we examined the PTOV1 expression status in 169 paraffin-embedded, archived breast cancer tissues by immunohistochemistry (IHC)." (PMID 24947166, 2014). "Furthermore, Cox regression analysis showed that higher PTOV1 expression was an independent prognostic indicator of shorter survival in breast cancer patients." (PMID 24947166, 2014). "Taken as a whole, these results indicate that PTOV1 could be a useful prognostic factor in breast cancer patients." (PMID 24947166, 2014). "A close correlation between PTOV1 expression and ER expression status (r = 0.246, P = 0.001) suggested that the expression level of PTOV1 might be a useful supplement to breast cancer hormone therapy decision-making." (PMID 24947166, 2014). "Our study indicated that PTOV1 might positively regulate breast cancer development and progression, and is a useful indicator of poor prognosis and a prognostic marker for patient survival." (PMID 24947166, 2014). "Univariate and multivariate analysis revealed that PTOV1 might be an independent prognostic factor for breast cancer patients (P = 0.005)." (PMID 24947166, 2014). "Cox regression analysis revealed that PTOV1 might be considered as an independent biomarker for breast cancer prognosis." (PMID 24947166, 2014). "However, the modulation of PTOV1 expression in this malignant tumor and its molecular mechanisms in breast cancer development and progression still require further investigation." (PMID 24947166, 2014). "In summary, these data suggested that PTOV1 is overexpressed in breast cancer tissues." (PMID 24947166, 2014). "Collectively, our findings strongly suggested that PTOV1 plays an important role in the development and progression of human breast cancer, and might be a useful predictive marker of prognosis in breast cancer patients." (PMID 24947166, 2014).